TCF3 (transcription factor 3)
Diseases named in the same sentence as TCF3 in open-access papers (continued):
Sharing a sentence is not in itself a finding about the gene and the disease.
tumor (continued). "Specifically, the characteristics and implications of TCF3 expression patterns have an impact on promoting tumor-related angiogenesis and reshaping the immunosuppressive TME." (PMID 39205642, 2024). "Then, we investigated the single nucleotide variant (SNV) frequency of TCF4, TCF3, and TCF7 in each tumor based on TCGA data." (PMID 39205642, 2024). "Collectively, these findings suggested that TCF3 plays a crucial role in promoting various stages of tumor progression, including EMT, migration, invasion, and angiogenesis." (PMID 39205642, 2024). "Our results show that TCF3/4/7 exhibits differential expression patterns between normal and tumor tissues across pan-cancer analyses." (PMID 39205642, 2024). "Another study reported that ASBEL is capable of promoting tumor formation by inhibiting ATF3 through interaction with TCF3." (PMID 39439418, 2024). "We assessed the difference in TCF3 expression between normal and tumor samples from the GSE36895 and GSE40435 datasets." (PMID 39205642, 2024). "To investigate the transcription pattern of the TCF/LEF family, we first compared the median levels of TCF7, TCF4, and TCF3 in normal and tumor tissues from pan-cancer patients in the TCGA cohort using FPKM and TPM expression values." (PMID 39205642, 2024). "In both databases, the tumor samples exhibited substantially increased expression of TCF3 (P < 0.05 in GSE36895,P < 0.001 in GSE40435)." (PMID 39205642, 2024). "Our analysis revealed that TCF3 was predominantly positively correlated with differentiation and quiescence across most tumor types, while it was negatively correlated with DNA repair in the majority of tumors." (PMID 39205642, 2024). "The results demonstrated that TCF3 was mainly expressed in the nucleoplasm and exhibited notably higher staining intensity in tumor tissues." (PMID 39205642, 2024). "We also determined the expression of TCF3 in the tumor tissues by immunoblotting analysis and immunohistochemistry, the results of which confirmed that TCF3 does promote the progression of ESCC in vivo." (PMID 37607071, 2023). "We found thatLEF1 and TCF3 are over-expressed in breasttumors regarding non-tumor samples, while TCF4 andTCF7 are down-expressed, with the gene’s methylation statusbeing associated with its expression dysregulation." (PMID 38100720, 2023). "Current evidence suggests that tumor-derived factors (TDFs) promote trogocytosis between CAR-expressing and tumor cells via activating transcription factor-3 (ATF3)." (PMID 37974170, 2023). "First, GEP analyses revealed that tumour cells from MM patients express higher levels of TCF3 than normal plasma cells, and that TCF3 expression correlates with disease progression in MM (GSE6477, GSE39754)." (PMID 36631435, 2023). "TCF3 expression level correlates with clinical stage, tumor size, TNM stage, grade, OS, disease-specific survival, and progression-free survival (PFS) in HCC patients." (PMID 35833147, 2022). "In summary, our findings show that the combined application of GSK126 and 5-Aza synergistically inhibited EZH2 and DNMT3B to derepress the expression of TCF3, and profoundly blocked EC tumor progression in mouse models." (PMID 34175897, 2021). "The accumulation of TCF3 is generally related to the growth and development of tumor cells, so TCF3 is considered to be a transcription factor that regulates tumor cell proliferation, migration, and invasion." (PMID 34658308, 2021). "Considerable studies had shown that TCF3 protein can act as either a tumor suppressor or an oncoprotein." (PMID 34175897, 2021). "To further characterize this putative EZH2/TCF3/p21 regulatory axis in vivo, we exploited a subcutaneous xenograft tumor model using KLE cells with EZH2 knockdown or TCF3 knockdown individually or simultaneously." (PMID 34175897, 2021).
tumor (continued). "The ID3 gene encodes the DNA-binding protein inhibitor ID-3, which is a helix-loop-helix protein involved in negatively regulating the DNA-binding transcription factor TCF3 and behaves as a tumor suppressor." (PMID 33801781, 2021). "In the first pathway, in early-stage CRC, the upregulated CASC2 transmits the signal to HINFP, which is modified by ubiquitination to inhibit tumor growth, and transmits the signal to TF TCF3 through SMG8." (PMID 32211020, 2020). "E2F1 (network 1, out-degree 147) can stimulate apoptosis and function as a tumor suppressor, while the TCF3 fusion (network 4, out-degree 207) has been found in adenocarcinomas in situ." (PMID 29303984, 2018). "This is in contrast with other transcription factors, such as TCF3, the expression of which was equal in all three tumor types." (PMID 29164272, 2018). "TCF3 overexpression downregulated the expression of Nanog mRNA and reduced tumor sphere formation and clone formation." (PMID 29299140, 2017). "Recent data suggest that re-expression of TCF3 induces apoptosis and cell-cycle arrest in cHL cell lines, indicating that TCF3 is an important tumour suppressor gene in the context of cHL." (PMID 28893938, 2017). "Although considerable studies had showed TCF3 was a tumor promoter, its role in cancer progression remains controversial." (PMID 25375219, 2014). "Ches1, Tcf3, Ccnc and Gfi1 are transcriptional repressors, Pten and Runx3 are tumor suppressors, and Cdkn1b is a cell cycle inhibitor." (PMID 24859236, 2014). "As a transcriptional repressor, the role of TCF3 is down-regulating E-cadherin during tumor progression." (PMID 25375219, 2014). "Previously, we demonstrated constitutive TCF activation in primary desmoid cell cultures and showed that β-catenin binds and activates TCF-3 in these tumours." (PMID 15054469, 2004). "In our previous work, we demonstrated β-catenin/TCF3-mediated transcriptional activation in desmoid tumours." (PMID 15054469, 2004). "Expression and co-immunoprecipitation studies suggest that β-catenin binds and activates tcf-3 in this tumour." (PMID 11437409, 2001). "In summary, TRIM21 could influence tumor development and chemosensitivity to replication inhibitors by regulating DNA replication through the TCF3/MCM2/5 axis, suggesting a promising potential for CRC in the clinic." (PMID 40998798, 2025). "Considering these results, we speculated that the activation of SEH1L and TCF3 observed in DOX-resistant tumor cells may be a consequence of compensatory mechanisms in response to xenobiotic stress." (PMID 41153808, 2025). "Since we had established that PRMT5-mediated H4R3me2s mark is sufficient to regulate TCF3 splicing which subsequently regulates tumor cell invasion, we asked if targeting dCAS9-PRMT5 to the TCF3 splicing locus will be sufficient to enhance invasion by altering TCF3 splicing event." (PMID 41150697, 2025). "Given that EMT has been shown to markedly diminish the sensitivity of tumor cells to chemotherapeutic agents, including DOX, we propose that observed overexpression of TCF3 in DOX-resistant cells may be linked to their partial mesenchymal phenotype." (PMID 41153808, 2025). "Additionally, cardiac remodeling promotes tumor growth, as transverse aortic constriction (TAC) favors primary tumor growth and cardiac dysfunction promotes metastasis through activating transcription factor 3 (ATF3)." (PMID 39846541, 2025). "To test our hypothesis and predict outcomes derived from bioinformatics, we conducted an IHC analysis of TCF3 to determine its expression pattern in tumor and adjacent normal tissues of KIRC." (PMID 39205642, 2024). "The analysis of the results of RNA-seq revealed that TCF3 may regulate the process of tumor development through the regulation of tumor stemness." (PMID 37607071, 2023). "Bioinformatic study showed that tumor stem cells activated TCF3, SMARCA4, TFF3, etc.." (PMID 37717019, 2023).
tumor (continued). "Thus, the reduction of TCF3 expression by miRNAs has a critical role in the inhibition of tumor initiation and development." (PMID 34700372, 2022). "TCF3 plays a fundamental role in tumor initiation and growth." (PMID 34700372, 2022). "TCF3 is regulated by androgens and acts as a tumor promoter in PCa." (PMID 28651018, 2017). "On the other hand, negative correlation of EZH2 (r = -0.53, p < 0.001), SALL4 (r = -0.4, p < 0.001), TCF3 (r = -0.45, p < 0.001) with Hp in high tumor Hp expression group could also be an indication of relative well cancer differentiation." (PMID 28158312, 2017). "In addition, we found tumor cell-specific loss of several transcription factors critical for maintaining differentiation: EBF1, TCF3 and RUNX1." (PMID 28692033, 2017). "Reductions of Ebf1, Tcf3 and Runx1 transcripts were also detected in EB tumor cells relative to lymph node cells from Bcl-xLTg control mice, confirming that levels of these transcripts are reduced even if the tumor cells are peripheral in origin." (PMID 28692033, 2017). "Contribution of TCF3 inactivation in oncogenesis have been described in other tumor entities." (PMID 27166193, 2016). "We conclude that inactivation of TCF3 contributes to oncogenic program of cHL and might be critical for tumor maintenance." (PMID 27166193, 2016). "Detectable quantities of the SNAI I (Snail) and TCF-3 (E2A) proteins in tumour and normal stromal cultures may also indicate active EMT/MET processes both in tumour stroma and surrounding presumably normal tissue." (PMID 20407446, 2010). "The circRNA signature in childhood TCF3::PBX1 subtype B-cell ALL, has identified cirANSK1B, cirBARD1, and cirMAN1A2 as overexpressed and potential biomarkers for prognosis and tumor detection." (PMID 40806675, 2025). "​In conclusion, we delineate a coherent oncogenic framework in which SE-driven TRIB2 expression is activated by TCF3, leading to NRF2 stabilization that suppresses ferroptosis and promotes tumor proliferation in HB." (PMID 41462308, 2025). "To address this issue, we calculated hazard ratio (HR) values for SEH1L, TUBA4A, TCF3, ZYX, and GJA1, both individually and in combination, using tumor data from The Cancer Genome Atlas (TCGA)." (PMID 41153808, 2025). "IHC staining of tumor tissues acquired on the day of sacrifice showed decreased MCM2, MCM5, BrdU and MKI67 levels in TRIM21 knockdown groups, contrasting with elevated TCF3 levels." (PMID 40998798, 2025). "Overall, the expressions of TCF7, TCF4, and TCF3, which are members of the TCF/LEF family of proteins, are significantly different between normal and tumor samples, indicating the potential involvement of TCF/LEF in the occurrence and progression of cancers." (PMID 39205642, 2024). "Both the sarco-sphere model as well as the corresponding tumor tissue harbored an in-frame EIF5A::USP6 fusion in chromosome 17, homozygous losses of CDKN2A/B and ATRK, a truncation in the NOTCH1 gene and a TCF3::SLC39A3 rearrangement." (PMID 37951844, 2024). "In conclusion, this study is the first to reveal that TCF-3, a member of the TCF/LEF family, plays a significant role in tumor biology and alterations in the TME, with potential clinical implications." (PMID 39205642, 2024).
tumor (continued). "Immunohistochemical analyses of harvested tumours confirmed downregulation of NCP26 targets, including MYC, CCND1 and TCF3, and ISR engagement, evidenced by induction of p-GCN2 and DDIT3." (PMID 36631435, 2023). "The expressions of FEN1 and TCF3 were mainly enriched in pit mucous and grand mucous cells, while SERPINE1 was mainly expressed in tumor cells." (PMID 37100457, 2023). "While E2A/TCF3 is annotated as a tumor suppressor gene (TSGene 2.0) with direct experimental and clinical evidence, HEB/TCF12 tumor suppressor function has been overlooked, despite the critical role of HEB in the T lineage." (PMID 35401501, 2022). "In the current study, we identified TCF3 as a direct target of EZH2 and DNMT3B, which acts as a tumor suppressor in EC." (PMID 34175897, 2021). "In high tumor Hp expression group, EZH2 (r = -0.53, p < 0.001), SALL4 (r = -0.4, p < 0.001), TCF3 (r = -0.45, p < 0.001) were also negatively correlated with Hp." (PMID 28158312, 2017). "In this dataset, positive TCF3, ID1 and ID4 expression were more frequent (Chi-square test, p = 0.033, p<0.001, and p<0.001, respectively) in the basal-like tumours." (PMID 23555842, 2013). "In addition, both TCF3 and TRIB2 were significantly overexpressed in HB compared with non-tumor tissues across two independent cohorts (GSE132219 and GSE104766)." (PMID 41462308, 2025). "Our study demonstrated that TCF3 suppressed CRC development by modulating DNA replication through repressing MCM2 and MCM5 transcription, providing a novel mechanistic insight into its tumor-suppressive function." (PMID 40998798, 2025). "TCF3 primarily activates the Wnt/β-catenin signaling pathway, which is a key driver of cancer cell stemness properties and EMT promotion, the processes contributing to tumor progression and therapeutic resistance." (PMID 41153808, 2025). "So far, there have been no reports suggesting how TCF3 splicing is affected in tumor hypoxia and its role in orchestrating EMT and invasion." (PMID 41150697, 2025). "Our above results suggest that since AEBP1 cooperates with key transcription factor TCF3 downstream of the Wnt signaling in GC, the knockdown of AEBP1 may enhance the inhibitory effect of Wnt pathway inhibitors on tumor metastasis." (PMID 40296906, 2025). "Nonetheless, TCF3 mRNA is highly expressed in human T-ALL and the TCF3 gene is neither deleted nor mutated, raising the question how E2A acts as a tumor suppressor." (PMID 35401501, 2022). "Taken together, these results demonstrate that TCF3 is a direct target of EZH2, which may act as a tumor suppressor to inhibit proliferation of EC cells." (PMID 34175897, 2021). "Given that TCF3 is not only an essential regulator in B- and T- lymphocyte development, but also a tumor suppressor in T cell tumors, our finding is not surprising." (PMID 27166193, 2016). "Interestingly, stromal cells of all tumour and normal cultures expressed detectable quantities of the SNAI I (Snail) and TCF-3 (E2A) proteins known to be transcriptional repressors of the CDH1 gene and potential inducers of EMT." (PMID 20407446, 2010). "The role of TCF3 repression in cHL lymphomagenesis has not been addressed so far, but there are several lines of evidences indicating that it may act as a tumor suppressor." (PMID 27166193, 2016). "Taken together, these results demonstrate that the Tcf3-Tal1 complex dominates in the absence of the Id2 HLH domain and recruits LSD1 to alter chromatin accessibility at the Slamf6 promoter during the Texprog-to-Texterm conversion in tumor immune evasion." (PMID 38287103, 2024).
cancer (79 papers, 2007 to 2025). A tumor composed of atypical neoplastic, often pleomorphic cells that invade other tissues. "The limited prior association of SEH1L, TUBA4A, ZYX, and TCF3 with chemoresistance, combined with their consistent dysregulation across cancer types, nominates them as novel and promising biomarker candidates for predicting DOX sensitivity." (PMID 41153808, 2025). "We further investigated the association between TCF3 and 14 distinct cancer functional states utilizing single-cell sequencing data from CancerSEA." (PMID 39205642, 2024). "In this study, we identified distinct TCF3 expression patterns in large-scale cancer cohorts that were strongly associated with differences in the clinicopathological features of the TME." (PMID 39205642, 2024). "After inspecting the mutation landscape, we investigated the impact of TCF3 on pan-cancer PFS and OS." (PMID 39205642, 2024). "Previous works have suggested that silencing of TCF3 by RNAi causes cell cycle arrest at the G2 phase and represses the proliferation of cancer cells." (PMID 34700372, 2022). "TCF3 knockdown inhibits cancer cell proliferation and cell cycle, which is associated with dysregulation of the WNT signaling mechanism." (PMID 35833147, 2022). "In contrast, the overexpression of miR-449a in Nanogneg cancer cells promoted stemness-associated features (self-renewal ability and tumorigenicity), and restoring TCF3 expression in these cells negated the enhanced stemness." (PMID 29299140, 2017). "Interestingly, we found that SEH1L and TCF3 activation was associated with increased chemosensitivity to DOX in vitro in the Cancer Therapeutics Response Portal database, contrasting with our clinical findings." (PMID 41153808, 2025). "Additionally, our CIBERSORT analysis revealed a significant association between TCF3 expression and the level of immune cell infiltration in most cancer types." (PMID 39205642, 2024). "Subsequently, we performed a pan-cancer analysis of TCF3 mutations in the TCGA database." (PMID 39205642, 2024). "In several cancer types, TCF3 over-expression is associated withtumorigenic processes." (PMID 38100720, 2023). "In addition to TERT, BLCAP, and KBTBD8, we also observed low levels of damage induction in UV-irradiated melanocytes at a number of other recurrent mutations in the promoters of known or suspected cancer genes (i.e., TCF3, TOP2A, NUMB, FOSB, and OTUB2)." (PMID 37169747, 2023). "The binding affinity of miRNAs could be affected by SNPs at 3′ UTR of the TCF3 gene, which could be associated with the increased risk of different cancers, including BC and GC." (PMID 34700372, 2022). "However, the disease-free survival rate was significantly lower in patients with high TCF3 protein expression than in those with low expression (P = 0.002), and TCF3 expression was significantly associated with histological type of cancer (P = 0.038)." (PMID 25375219, 2014). "Therefore, maintaining cancer stemness might be the underlying mechanism that TCF3 transcriptionally regulated ID1 and further promoted ESCC progression and drug resistance." (PMID 37607071, 2023). "Furthermore, rs72618599 may be associated with cancer progression by altering the regulatory affinity of hsa-miR526b-5p to 3′-UTR of TCF3." (PMID 34700372, 2022). "Though class I bHLH TFs (TCF3, TCF4, and TCF12) are important for cancer, development, and immunity, and associated with neural disorders, how they functionally contribute to these processes is poorly understood." (PMID 39119816, 2025). "Of these genes, this analysis highlighted 176 genes as functionally relevant to human disease and/or cancer or cancer-related mechanisms, including TCF3." (PMID 40766465, 2025). "Our findings revealed high expression of TCF3 in cancer tissues, with a shorter overall survival observed in the high-expression TCF3 group compared to the low-expression group." (PMID 40610429, 2025).